KCNQ1 (potassium voltage-gated channel subfamily Q member 1)
Diseases named in the same sentence as KCNQ1 in open-access papers (continued):
Sharing a sentence is not in itself a finding about the gene and the disease.
Arrhythmia (continued). "Although AC9 labeled few selective cardiac proteins, its proximity to AKAP5 and SNTA1 (and weak labeling of KCNQ1, SS = 0.5) is in accord with its roles in cardiac repolarization and inheritable arrhythmias." (PMID 40749829, 2025). "However, KCNQ1-inhibitor gefitinib, which is the first-generation targeted therapy for non-small cell lung cancer, was implicated in the induction of heart QT prolongation in a guinea pig model, thereby raising a concern of arrhythmia when gefitinib is used for NSCLC treatment." (PMID 38911514, 2024). "Loss-of-function mutations in KCNQ1 cause LQT1, characterized by a prolonged APD and increased susceptibility to exertion triggered lethal cardiac arrhythmias." (PMID 37650513, 2023). "The results indicated that KCNQ1−/− CMs show obvious arrhythmia and that the proportion of EADs significantly increased compared with WT CMs." (PMID 35765105, 2022). "Most of these variants were located in genes associated with inherited arrhythmias and arrhythmic cardiomyopathies, such as MYBPC3, KCNQ1, TTN, CASQ2, GPD1L, DPP6, HCN4 and NEXN." (PMID 36008935, 2022). "Under ISO stimulation, all models showed aggravation of the arrhythmia phenotype, partially simulated LQT1 caused by KCNQ1 mutation under sympathetic excitation." (PMID 35765105, 2022). "Klotho counteracts cardiac arrhythmia by ensuring the cell surface expression of KCNQ1/KCNE1 K+ channels that are involved in cardiac repolarization." (PMID 35406743, 2022). "Gain-of-function (GOF) mutations in the voltage-gated potassium channel subfamily Q member 1 (KCNQ1) can induce cardiac arrhythmia." (PMID 33600800, 2021). "Decrease in KCNQ1/KCNE1 current is known to be associated with prolongation of action potential and cardiac arrhythmias." (PMID 34907346, 2021). "A decrease in the slow delayed rectifier potassium current (IKs) due to mutations in the alpha subunit of the channel, KCNQ1, leads to prolongation of the QT interval on the ECG which underlies the development of inherited cardiac arrhythmias (LQT1)." (PMID 34907346, 2021). "Dysfunctional KCNQ1/KCNE1 channels prolong the APD and cause life-threatening LQTS and cardiac arrhythmias." (PMID 33322401, 2020). "In human KCNQ1, a mutation of the equivalent residue to histidine (R243H) reduces PIP2 affinity and is associated with the cardiac arrhythmia, long QT syndrome." (PMID 32655402, 2020). "Loss-of-function (LOF) mutations in KCNQ1 are the most common cause of congenital long QT syndrome (LQTS), type 1 LQTS, an inherited genetic predisposition to cardiac arrhythmia and sudden cardiac death." (PMID 31518351, 2019). "Variants in two ion channel genes (CACNA1C and KCNQ1) have been identified in patients with mixed HCM and arrhythmia phenotypes but are suggested to be responsible for the arrhythmic rather than hypertrophic component of the phenotype in these cases." (PMID 28082330, 2017). "In one study, both patient-derived and engineered hiPSCs carrying the E160fs + 138X or the R594Q KCNQ1 mutations recapitulated the severe JLNS electrophysiological phenotype including APD prolongation and drug-induced arrhythmia susceptibility." (PMID 28573431, 2017). "While hERG channels are responsible for the largest proportion of drug-induced TdP arrhythmias, KCNQ1/MinK channels pass the slow cardiac delayed rectifier current IKs and also play a significant role in such arrhythmias." (PMID 22039467, 2011). "Congenital long QT syndrome type I is a cardiac disorder in which defects in KCNQ1, a voltage-gated potassium channel, result in serious cardiac arrhythmias." (PMID 22085535, 2011). "Here, we present the first such analysis of arrhythmia-associated mutations (AAMs) in the HERG and KCNQ1 potassium channels." (PMID 18590565, 2008). "Furthermore, in a mouse model of LQT1 (Kcnq1 mutation), there is a high prevalence and concordance of EEG abnormalities, seizures, autonomic instability, ECG abnormalities, and arrhythmias." (PMID 35600076, 2022).
Arrhythmia (continued). "KCNQ1 is curated as one of the definitive genes for arrythmia, while its clinical implications and biological roles in LUAD remain unclear." (PMID 35216393, 2022). "Consequently, PBA derivatives more selective for cardiac KCNQ1/KCNE1 channels can be potent activators for treatment of cardiac arrhythmias." (PMID 33322401, 2020). "To this end, we determined the effects of the sEHI trans-4-[4-(3-adamantan-1-yl-ureido)-cyclohexyloxy]-benzoic acid (t-AUCB) on the expression of miR-133, its target arrhythmia–related genes (KCNQ1 and KCNH2), and serum response factor (SRF), an important transcriptional factor in cardiomyocytes." (PMID 29843720, 2018). "It is now well established that KCNQ1 channels assemble with KCNE β-subunits for correct physiological function; mutations that disrupt this complex formation result in congenital deafness and inherited cardiac arrhythmias." (PMID 19623261, 2009). "The different patterns of nsSNP distribution between the KCNQ1 and HERG underscore the need to identify and quantitatively analyze the distribution of more nsSNPs on each protein, and to ascertain their impact on channel function and arrhythmia susceptibility." (PMID 18590565, 2008). "However, there are a few exceptions: patients with Timothy syndrome, patients with Jervell Lange-Nielsen syndrome carrying KCNQ1 mutations and LQT3 patients with 2:1 atrio-ventricular block and very early occurrence of cardiac arrhythmias." (PMID 18606002, 2008). "Further investigation into other potential genetic biomarkers, including arrhythmogenic genes such as KCNQ1 and SCN5A is required, as are studies into how acute seizures or long‐term seizure‐related changes in cardiac function interact with genetic causes of arrhythmia." (PMID 34002542, 2021). "Propranolol can improve the arrhythmia phenotype of the three KCNQ1-mutant myocardial models, including KCNQ1−/− CMs, indicating that propranolol has therapeutic effects on LQT1 through multiple mechanisms." (PMID 35765105, 2022). "One study suggested that the repolarization reserve of KCNQ1/KCNE1 channels is important to prevent the development of ischemia- and reperfusion-induced arrhythmias." (PMID 33322401, 2020). "Recently, PUFAs have drawn more and more attention as they have been demonstrated to activate KCNQ1/KCNE1 channels efficiently, making PUFAs a promising approach for treating LQTS and cardiac arrhythmias." (PMID 33322401, 2020). "KCNQ1/KCNH2 suppression-and-replacement, SCN5A base editing, and structural protein restoration via PKP2 and TMEM43 have each demonstrated capacity to re-establish electrophysiological stability in arrhythmia models." (PMID 42193469, 2026). "Knowing that consanguinity was not present, the Inherited Arrhythmias Clinic pursued Multiplex Ligation-Dependent Probe Amplification (MLPA) and identified a deletion of exon 3 in the second KCNQ1 allele (ΔExon 3)." (PMID 39786967, 2025). "Modulation of KCNQ1 and KCNE1 might be the mechanism of puerarin in the clinic treatment of arrhythmia." (PMID 27762288, 2016). "Therefore, a reduction in KCNQ1/KCNE1 might play a similar role in developing arrhythmia in both congenital LQTS and ischemia- and reperfusion-induced arrhythmias." (PMID 33322401, 2020).
diabetes (74 papers, 2009 to 2025). "Through cell biology experiments and animal studies, we will further elucidate the mechanism of the KCNQ1 risk gene and diabetes susceptibility." (PMID 40671906, 2025). "Overall, this study sheds light on the role of KCNQ1 mutations in pancreatic function and their contribution to diabetes development." (PMID 40650956, 2025). "Previous research has found associations with variants tied to obesity and diabetes, including SNPs in KCNQ1, PPARG, and GNB312–19." (PMID 38854080, 2024). "Methylation of the TXNIP gene (thioredoxin-interacting protein) and KCNQ1 (potassium voltage-gated channel subfamily Q member 1) was previously shown to associate with the development of diabetes complications." (PMID 36633903, 2023). "In contrast, KCNQ1 polymorphisms are associated with diabetes, and LQTS patients have a higher prevalence of diabetes." (PMID 34112814, 2021). "The most interesting literature linking KCNQ1 to ARHL comes from the diabetes field, which constitutes a risk factor for ARHL." (PMID 33336302, 2021). "It has been confirmed that the KCNQ1 gene was associated with diabetes, metabolic syndrome, and lipid parameters." (PMID 32390949, 2020). "On the other hand, referring to the causal inference, MetS was a risk factor for diabetes and the KCNQ1 gene was associated with diabetes." (PMID 30157802, 2018). "It has been confirmed that the KCNQ1 gene was associated with diabetes in population of both Asian and European descent." (PMID 30157802, 2018). "Most studies indicated that the KCNQ1 gene was a diabetes susceptibility gene in different ancestors." (PMID 30157802, 2018). "In a study among American Indians from central Arizona, KCNQ1 variants were associated with incident diabetes." (PMID 30369944, 2018). "The patients with diabetes carrying the KCNQ1 rs2237895 C allele had a smaller change in both fasting insulin level and HOMA-IR." (PMID 30065651, 2018). "Previous studies have reported that the potassium voltage-gated channel subfamily Q member 1 (KCNQ1) gene is associated with diabetes in both European and Asian population." (PMID 30157802, 2018). "rs231356-T, which was associated with hypomethylation of cg26963277 (KCNQ1), was associated with a higher odds of diabetes (OR 1.06, p = 1.3 × 10−5)." (PMID 26825526, 2016). "A recent study of individuals with diabetes from Japan identified variants in the KCNQ1 gene in association with diabetic nephropathy." (PMID 21931561, 2011). "We also evaluated the most significant SNP (rs231361) within KCNQ1, which was previously reported to be a diabetes susceptibility gene in a Japanese population, as well as in populations of Korean, Chinese, and European ancestry." (PMID 20174558, 2010). "GWAS study in Japanese population also identified KCNQ1 as a diabetes susceptibility loci which was further confirmed in other population." (PMID 20625434, 2010). "Some of the genes associated with both monogenic (ABCC8 and KCNJ11) and complex diabetes (KCNJ11, KCNQ1) encode subunits of these potassium channels and accordingly, monogenic diabetes of this type can be well managed with sulfonylureas." (PMID 19794883, 2009). "Interestingly, patients with LQTS are more likely to have diabetes than the general population, highlighting a paradoxical link between hyperinsulinemia and heart conditions, with KCNQ1 identified as a risk gene for T2D." (PMID 40650956, 2025). "Likewise, we observed that the hypomethylated CpG cg00382572 position is assigned to the KCNQ1 gene coding for the KCNQ1 potassium channel, which is located in the pancreas and has been also associated with diabetes." (PMID 37587247, 2023). "In terms of diabetes complications, it was suggested that the KCNQ1 rs2237892 variant may contribute to susceptibility in macrovascular disease, diabetic nephropathy, and diabetic retinopathy." (PMID 34442333, 2021).
diabetes (continued). "There is compelling evidence that diabetes risk at the KCNQ1 locus is medicated through a gene with imprinted gene expression that may be mediated by KCNQ1 or neighboring genes (KCNQ1OT1 or CDKN1C)." (PMID 33336302, 2021). "Second top signal in IROD2 group of long-term diabetes suggested reduced frequency of the risk allele in the imprinting gene KCNQ1 (rs 163,184) that has also been shown to be expressed in the pancreatic β-cells and to act through impaired islet function on the risk of future T2D." (PMID 34276762, 2021). "In analyses of diabetes candidate genes, we identified an association with several variants near KCNQ1, which encodes a voltage-gated potassium channel and has been associated with diabetes in individuals of European and East Asian ancestries but also in Southwest American Indians." (PMID 30369944, 2018). "We also validated associations of GCK and KCNQ1 variants with diabetes in our study population." (PMID 30369944, 2018). "In addition, SNP rs2237892 located within gene KCNQ1 was found to be associated with both overweight and obesity and diabetes at first [19." (PMID 24959828, 2014). "Therefore, it is important to examine the association between the KCNQ1 variants and metabolic traits to elucidate the underlying diabetes-causing mechanisms." (PMID 22403629, 2012). "Thus, it is unlikely that our observed associations are solely due to the association of KCNQ1 with diabetes." (PMID 21931561, 2011). "Risk alleles in KCNQ1 confer a risk for T2D only when inherited by the mother and influence methylation levels of regulatory sequences in fetal human pancreas, suggesting that some diabetes risk effects may be mediated in early development." (PMID 37291636, 2023). "Although we did not observe an association between DNA methylation at cg26963277 and expression of KCNQ1, our results provide evidence that smoking may increase the risk of diabetes through decreased methylation at KCNQ1 and a subsequent decrease in fasting insulin levels." (PMID 26825526, 2016). "However, whether KCNQ1 variants are associated with the diseases other than long QT syndrome and diabetes need to be further examined." (PMID 26678516, 2015). "The enrichment of TCF7L2, KCNQ1, and CDKAL1 variants in specific subtypes highlights the potential for integrating genetic screening into diabetes stratification models." (PMID 41422334, 2025). "The results show that KCNQ1 was decreased compared with the normal control group, which indicates that diabetes can damage the KCNQ1 of blood vessels." (PMID 41035911, 2025). "Our study provides a better understanding of the role of KCNQ1 in regulating insulin secretion and β-cell survival in hereditary diabetes pathology." (PMID 39055936, 2024). "SNPs in the TCF7L2, KCNQ1, and KCNJ11 genes were studied, and the results confirmed that these three SNPs were associated with all types of diabetes studied, including T2DM, GDM, and PTDM." (PMID 37107681, 2023). "Variants near candidate diabetes genes (especially GCK and KCNQ1) were also nominally associated with HOMA-IR and cHOMA-B." (PMID 30369944, 2018). "A genetic risk score based on the diabetes risk alleles TCF7L2 rs7903146, KCNQ1 rs163184, KCNQ1 rs2237892, GIPR rs10423928 and WFS1 rs10010131 also showed a nominally significant interaction with coffee intake (p = 0.005)." (PMID 27623947, 2016). "Not only did we find TCF7L2 and KCNQ1 variants to be associated to GDM, but GDM cases reported higher frequency of family history of diabetes than controls." (PMID 25973943, 2015). "Potassium voltage-gated channel, KQT-like subfamily, member 1 (KCNQ1) is thought to be an important candidate gene of diabetes." (PMID 22479571, 2012). "The predictive effect of KCNQ1 gene for incident diabetes and the potential mechanism of this gene in the pathogenesis of T2DM remain to be explored." (PMID 21103332, 2010). "For example, KCNQ1, known as a diabetes-related gene, had the lowest attributed value." (PMID 40163718, 2025).
diabetes (continued). "We identified a homozygous KCNQ1 mutation (R397W) in an individual with permanent neonatal diabetes melitus (PNDM) without cardiovascular symptoms." (PMID 39055936, 2024). "Expression of both KCNQ1 and CDKN1C demonstrated to exhibit temporal effects in fetal and adult human pancreas and islets emphasizing that the diabetes risk may be mediated in early development." (PMID 34276762, 2021). "Activation by Mallotus compounds of KCNQ1 alone and in complexes with KCNEs may contribute to its purported therapeutic effects in GI and cardiovascular disorders and diabetes given the known roles of KCNQ1 in these systems." (PMID 32655402, 2020). "Among genetic variants, the diabetes-associated variants in TCF7L2 (rs7903146) and WFS1 (rs10010131) have been shown to affect the response to exogenous GLP-1, while variants in KCNQ1 (rs151290, rs2237892, and rs2237895) have been reported to alter endogenous GLP-1 secretion." (PMID 25785276, 2015). "Furthermore, KCNQ1 SNPs, haplotypes and diplotypes were associated with beta-cell function in normal subjects without diabetes and metabolic syndrome." (PMID 22016621, 2011). "A SNP residing in KCNQ1 that is maternally associated with diabetes is a maternal eQTL of CDKN1C, not KCNQ1." (PMID 40502026, 2025). "The primary aim was to assess the relationship between DNA methylation at the KCNQ1 locus and measures of insulin sensitivity and β-cell function in a cohort of healthy individuals without diabetes." (PMID 30641161, 2019). "DNA methylation from whole blood DNA was quantified using pyrosequencing at 5 CpG sites at the KCNQ1 locus in 510 individuals without diabetes from the ‘Relationship between Insulin Sensitivity and Cardiovascular disease’ (RISC) cohort." (PMID 30641161, 2019). "Previous studies have reported differential DNA methylation at the KCNQ1 locus in pancreatic islets and adipose tissue of diabetes cases and non-diabetes controls." (PMID 26825526, 2016). "The associations of 23 SNPs located within 17 candidate genes (MTHFR, PPARγ, LPL, INSIG, TCF7L2, FTO, KCNJ11, JAZF1, CDKN2A/B, ADIPOQ, WFS1, CDKAL1, IGF2BP2, KCNQ1, MTNR1B, IRS1, ACE) with overweight and obesity, diabetes, metabolic phenotypes, and MetS were examined in both studies." (PMID 24959828, 2014). "The KCNQ1 SNPs rs2237892, rs2283228 and rs2237895 were genotyped in 300 T2D patients and 230 control subjects without diabetes and metabolic syndrome." (PMID 22016621, 2011). "The sample size of the PaC cases and controls without diabetes (448 cases and 557 controls), was likely underpowered as well, but our findings on DGKB-TMEM195 rs2191348, KCNQ1 rs231362, ADCY5 rs2877716 and BCL11A rs243021 may warrant further evaluation from larger studies." (PMID 25658847, 2015).